PLBD1 (phospholipase B domain containing 1)
Description:
Lysosomal processive monoaminopeptidase that preferentially cleaves hydrophobic amino acids, with strong preference for leucine residues. Plays a key role in the degradation of hydrophobic transmembrane domains within the lysosome.
Synonyms: LyLAP; PLBL1; FLJ22662
Tractability: Antibody: UniProt predicts a signal peptide or a membrane-spanning region; its Gene Ontology location is reachable by antibodies, with medium confidence. PROTAC: its protein half-life has been measured.
Gene: Protein-coding gene on chromosome 12 (14,503,660 to 14,567,913, reverse strand). Ensembl gene ENSG00000121316.
Subcellular location: Lysosome
Pathways (Reactome):
Metabolism: Acyl chain remodelling of PC; Acyl chain remodelling of PE; Acyl chain remodelling of PI; Hydrolysis of LPC
Gene Ontology:
Molecular function: aminopeptidase activity; phospholipase activity
Biological process: lysosomal protein catabolic process
Cellular component: extracellular region; lysosome; cytosol
Genetic constraint (gnomAD): Loss-of-function variants: 49 observed, 50.69 expected, observed/expected ratio (o/e) 0.97, 90% interval 0.77 to 1.23. The upper end of that interval is the gene's LOEUF score, 1.23, which puts it in group 5 of 6, group 1 being the genes least tolerant of losing a copy. Missense variants: 480 observed, 546.24 expected, observed/expected ratio (o/e) 0.88, 90% interval 0.81 to 0.95. Synonymous variants: 207 observed, 195.33 expected, observed/expected ratio (o/e) 1.06, 90% interval 0.94 to 1.19.
Homologues: Orthologues: chimpanzee PLBD1 (99% identical), macaque PLBD1 (93% identical), rabbit PLBD1 (86% identical), guinea pig PLBD1 (82% identical), pig PLBD1 (81% identical), dog PLBD1 (80% identical), mouse Plbd1 (77% identical), rat Plbd1 (76% identical), zebrafish plbd1a (54% identical), zebrafish plbd1b (50% identical), Caenorhabditis elegans F09B12.3 (32% identical), Caenorhabditis elegans Y54F10AM.8 (31% identical), and 1 more. Paralogues in human: PLBD2 (33% identical).
Diseases named in the same sentence as PLBD1 in open-access papers:
PLBD1 is named in the same sentence as 20 diseases in open-access papers, as found by Europe PMC text mining. Sharing a sentence is not in itself a finding about the gene and the disease. The quoted sentences say what the papers report.
glioma (4 papers, 2021 to 2024). A benign or malignant brain and spinal cord tumor that arises from glial cells (astrocytes, oligodendrocytes, ependymal cells). "Immunological profiling demonstrated that PLBD1 was significantly associated with immune cell infiltration and multiple immune checkpoints in gliomas and is a potential biomarker for gliomas." (PMID 38911364, 2024). "In addition, we found that the epigenetic alterations of PLBD1 were highly heterogeneous in a variety of cancers, including gliomas, and that its high methylation was associated with poor prognosis in a broad range of cancers." (PMID 38911364, 2024). "We also observed a significant positive correlation between PLBD1 and several steps of the cancer immune cycle in gliomas." (PMID 38911364, 2024). "PLBD1 expression was also significantly correlated with immune cell infiltration of gliomas, immune cycling, and immunotherapy." (PMID 38911364, 2024). "In this study, we explored the expression and prognosis of PLBD1 in various cancers using public databases and confirm its high expression levels in glioma clinical samples." (PMID 38911364, 2024). "The results showed that PLBD1 was significantly enriched in high-grade glioma (especially GBM), non-1p/19q deletion status and IDH wild-type in TCGA, CGGA-693 and CGGA-325 datasets." (PMID 38911364, 2024). "PLBD1 expression was strongly correlated with the prognosis of gliomas, glioma cell proliferation and invasion, which was preliminarily validated in cellular models." (PMID 38911364, 2024). "In gliomas, PLBD1 was expressed to a significantly higher extent in GBM than in LGG, and the expression of PLBD1 was higher in patients with IDH mutations than in patients with IDH wild-type, which is thought to be the key to better prognosis." (PMID 38911364, 2024). "We further knocked down PLBD1 in glioma cells and found that the proliferation and invasive ability of glioma cells were significantly reduced." (PMID 38911364, 2024). "In conclusion, PLBD1 is a potential tumor prognostic biomarker and immunotherapeutic target that plays a crucial role in glioma cell proliferation, invasion and immunotherapy." (PMID 38911364, 2024). "It was found that, consistent with database results, PLBD1 expression increased with the grade of glioma and was highest in GBM." (PMID 38911364, 2024). "In summary, although we have performed cellular experiments in vitro to investigate the biological function of PLBD1 in gliomas, further biological assays in vivo are needed to confirm our findings and to explore the mechanism of action in depth." (PMID 38911364, 2024). "The prognostic results showed that glioma patients with high PLBD1 expression had a significantly shorter survival time than those with low PLBD1 expression in TCGA, CGGA-693 and CGGA-325 datasets." (PMID 38911364, 2024). "The EdU results showed that compared to the control group, the ratio of proliferating glioma cells in the PLBD1 knockdown groups were significantly reduced." (PMID 38911364, 2024). "We then combined the expression and prognosis matrix of TCGA-LGG and TCGA-GBM and assessed the expression, prognostic significance and the functional enrichment of PLBD1 in glioma." (PMID 38911364, 2024). "To validate the expression of PLBD1 in glioma datasets, we further examined the PLBD1 expression in our patients' samples by western blots and IHC." (PMID 38911364, 2024). "Our results suggest that PLBD1 is highly expressed in multiple types of cancers, and it can serve as an independent prognostic factor for gliomas." (PMID 38911364, 2024). "The CIBERSORT showed that PLBD1 in the glioma had a significant correlation with various immune cells such as macrophages, neutrophils and Tregs." (PMID 38911364, 2024). "Furthermore, cellular experiments showed that knockdown of PLBD1 significantly inhibited the proliferation and invasive ability of glioma cells." (PMID 38911364, 2024). "We first explored the function of PLBD1 in glioma in TCGA dataset." (PMID 38911364, 2024).
glioma (continued). "Moreover, the Transwell results indicated that compared to the control group, the number of invaded glioma cells in the PLBD1 knockdown groups were significantly decreased." (PMID 38911364, 2024). "In addition, molecular biology experiments were performed in glioma cell lines to further validate the oncogenic function of PLBD1." (PMID 38911364, 2024). "In addition, the expression of major histocompatibility complex (MHC) molecules was upregulated in glioma in PLBD1 high-expression group, suggesting the increasing antigen presentation abilities." (PMID 38911364, 2024). "Furthermore, we assessed the impact of PLBD1 knockdown on the proliferation and invasive capacity of glioma cells by in vitro experiments." (PMID 38911364, 2024). "In brief, PLBD1 is considered a promising biomarker for predicting the prognosis of gliomas, which may inform the achievement of more precise individualized immunotherapy in the future." (PMID 38911364, 2024). "In addition, we examined the pan-cancer immunological signature of PLBD1, particularly in gliomas." (PMID 38911364, 2024). "Considering the expression of PLBD1 with in LGG and GBM and its correlation with prognosis and immune characteristics, we further evaluated the role and clinical value of PLBD1 in gliomas." (PMID 38911364, 2024). "In glioma grade III, highly activated DEGs included CFAP45, PLBD1, RASSF9, IGKV3-11, IGKV1-5, and NTS, while highly downregulated DEGs included NPAS4 and LINC01007." (PMID 33948562, 2021). "The results showed that the expression of PLBD1 was absent in normal brain tissues and positively correlated with glioma grade." (PMID 38911364, 2024). "Interestingly, not much is known about the functions of OTUD1, TCHH, ADPRH, PLBD1, and QPCT in glioma, which need further research in future." (PMID 36389681, 2022). "However, the correlation between PLBD1 and tumor including glioma has not been thoroughly evaluated." (PMID 38911364, 2024).
psoriasis (3 papers, 2023 to 2024). An autoimmune condition characterized by red, well-delineated plaques with silvery scales that are usually on the extensor surfaces and scalp. "Decision curve analysis (DCA) demonstrated that the nomogram provided superior clinical utility in predicting psoriasis occurrence probability at a high-risk threshold of 0–1, compared to individual curves for S100A7, SERPINB13, and PLBD1." (PMID 38699235, 2024). "Further investigation is warranted to fully elucidate the role of PLBD1 in psoriasis and its potential as a therapeutic target." (PMID 38699235, 2024). "Despite the lack of previous research investigating the relationship between PLBD1 and psoriasis, our study has uncovered evidence suggesting that this gene may hold significant promise as a target for the treatment of psoriasis." (PMID 38699235, 2024). "Our findings indicate that S100A7, SERPINB13, and PLBD1 may contribute to the inflammatory process of psoriasis by impacting macrophages infiltration, especially in LS samples." (PMID 38699235, 2024). "By targeting PLBD1, we may be able to develop more effective and precisely tailored treatments for psoriasis that improve patient outcomes." (PMID 38699235, 2024). "In addition, PLBD1 may be used as a prognostic biomarker for psoriasis and as a target for the treatment of patients with psoriasis." (PMID 38911364, 2024).
acute myocardial infarction (2 papers, 2024 to 2025). Necrosis of the myocardium, as a result of interruption of the blood supply to the area. "The study suggests that the RNA expression level of PLBD1 in peripheral blood can be a novel and independent predictor of left ventricular insufficiency after acute myocardial infarction, ischemic stroke, and aneurysm subarachnoid hemorrhage 9-11." (PMID 38911364, 2024). "The study suggests that PLBD1 RNA expression in peripheral blood may be a novel and independent predictor of left ventricular insufficiency after acute myocardial infarction 9, and PLBD1 also serve as a characteristic transcription factor in peripheral blood of ischemic stroke patients." (PMID 38911364, 2024).
COVID-19 (2 papers, 2022 to 2024). A disease caused by infection with severe acute respiratory syndrome coronavirus 2. "Of the 52 well-described IPF signature genes in our study, only 7 were upregulated in COVID-19 patients with NP, whereas in the SP group, only few genes, namely PLBD1, S100A12, and MCEMP1, were upregulated." (PMID 39205185, 2024).
ischemic stroke (2 papers, 2024 to 2025). A stroke disorder caused by obstruction of blood flow to the brain, due to thrombotic (local blood clot formation) or embolic (due to a blood clot or other material traveling from another site) event.
Cerebral ischemia (1 paper, 2025). Restriction of arterial blood supply to the brain associated with insufficient oxygenation to support the metabolic requirements of the tissue. "During cerebral ischemia, anaerobic glycolysis is enhanced and lactate accumulates, promoting lactylation of phospholipase B domain containing 1 (PLBD1) at K155, stabilizing the protein and activating the NLRP3 inflammasome to exacerbate pyroptosis and inflammation." (PMID 41440006, 2025).
immune-mediated diabetes (1 paper, 2020). "PLBD1 has been found to be upregulated in various studies with five-fold increase in cell lines and in study where the effect of pancreatic β-cells inducing immune-mediated diabetes was studied." (PMID 33133160, 2020).
melanoma (1 paper, 2025). A malignant, usually aggressive tumor composed of atypical, neoplastic melanocytes. "Notably, two serine proteases—plasminogen (Plg) and the CAAX prenyl protease 1 homolog (Zmpste24)—were detected only in melanoma, while two metabolic serine hydrolases—phospholipase B-like 1 (Plbd1) and carboxylesterase 1F (Ces1f)—were found only in normal skin." (PMID 39934865, 2025).
pancreatic adenocarcinoma (1 paper, 2023). "In 2020, a group demonstrated that PLBD1, together with eight other genes, can be a biomarker for the diagnosis of pancreatic adenocarcinoma." (PMID 36837912, 2023).
pulmonary fibrosis (1 paper, 2022). Chronic progressive interstitial lung disorder characterized by the replacement of the lung tissue by connective tissue, leading to progressive dyspnea, respiratory failure, or right heart failure. "Five genes demonstrated concordant directions of effects between the ILA [IPF transcripts] and IPF scores (CXCR6, IL7R, LBH, LRRC39, PLBD1), suggesting these genes may represent important biologic processes in promoting the progression of pulmonary fibrosis." (PMID 35715807, 2022). "Thus, there is already evidence that IL7R, LBH, and CXCR6 are important for understanding processes that promote pulmonary fibrosis, and LRRC39 and PLBD1 are additional targets for future studies." (PMID 35715807, 2022).
Sepsis (1 paper, 2025). Sepsis is defined as life-threatening organ dysfunction caused by a dysregulated host response to infection. "In the training dataset, the expression of LILRA5, MGST1, PLBD1, and S100A9 was upregulated significantly in the sepsis group compared to the normal group." (PMID 40792106, 2025). "LILRA5, MGST1, PLBD1, and S100A9 were selected as hub genes and significantly upregulated in sepsis." (PMID 40792106, 2025). "Moreover, in the test datasets, the expression of LILRA5, MGST1, PLBD1, and S100A9 was significantly elevated in the sepsis group." (PMID 40792106, 2025).
subarachnoid hemorrhage (1 paper, 2019). A serious neurological disorder characterized by intracranial hemorrhage into the subarachnoid space. "Other greenyellow hubs were associated with endothelin-1 signaling (PLBD1, MAPK14, CASP4), which is implicated in cerebral vasospasm following subarachnoid hemorrhage." (PMID 30836997, 2019).
tumor (3 papers, 2023 to 2024). "Furthermore, we used 7 algorithms including ssGSEA, CIBERSORT, CIBERSORT-ABS, EPIC, XCELL, TIMER and MCPCOUNTER to assess the association of PLBD1 with immune cells in tumor microenvironment." (PMID 38911364, 2024). "We found that PLBD1 was positively correlated with immune scores and stromal scores and negatively correlated with tumor purity in multiple cancers." (PMID 38911364, 2024). "Considering the key role of PLBD1 in tumor immunity, we then evaluated the correlation between PLBD1 and immune cells, immune modulators, immune process and immunotherapy response." (PMID 38911364, 2024). "We performed single-cell analysis of PLBD1 in multiple cancer single-cell datasets via the TISCH platform to understand the main cell types expressing PLBD1 in the tumor microenvironment." (PMID 38911364, 2024). "To investigate the association between PLBD1 and immunological features, we calculated the immune score, stromal score, and tumor purity, and analyzed their correlation with PLBD1 expression." (PMID 38911364, 2024). "In the GSE125449 dataset, PLBD1 was highly expressed in tumor cells and macrophages." (PMID 38911364, 2024). "The results showed that PLBD1 was mainly expressed in macrophages and tumor cells." (PMID 38911364, 2024). "In view of this, we focused on exploring the impact of PLBD1 on tumor immune profiles." (PMID 38911364, 2024). "The results suggest that PLBD1 modulates tumor immunity in multiple cancer types." (PMID 38911364, 2024). "The results indicated that PLBD1 has a strong positive correlation with immune score and stromal score, and has a negative correlation with tumor purity in several cancers, including ACC, LGG, GBM, PRAD, etc." (PMID 38911364, 2024). "We found that the abundance and trend of PLBD1 expression in multiple tumors were not consistent, which may be related to tumor specificity and tumor microenvironment." (PMID 38911364, 2024).
cancer (2 papers, 2022 to 2024). A tumor composed of atypical neoplastic, often pleomorphic cells that invade other tissues. "Our analysis showed that PLBD1 expression was associated with TMB in 16 cancer types and MSI in 8 cancer types." (PMID 38911364, 2024). "In some cancer types, PLBD1 levels were associated with TMB, MSI, immune cell infiltration, expression of immunosuppressive molecules, and immunotherapeutic response." (PMID 38911364, 2024). "We also found that PLBD1 expression was adversely linked to T-cell recognition of cancer cells (step 6)." (PMID 38911364, 2024). "We assessed pan-cancer expression, methylation, and mutation data of PLBD1 by multiple databases to investigate its clinical prognostic value." (PMID 38911364, 2024). "Our findings indicate that PLBD1 is significantly highly expressed in a variety of cancers and significantly correlates with the prognosis of patients." (PMID 38911364, 2024). "Among the 24 cancer types with normal tissues, 10 cancer types had statistically significant expression of PLBD1 in normal tissues and tumors." (PMID 38911364, 2024). "In this study, we performed a complete bioinformatics analysis using patient data from different repositories to determine the functional role of PLBD1 in a wide range of cancers." (PMID 38911364, 2024). "The results showed that the methylation level of PLBD1 was negatively correlated with its mRNA expression to varying degrees in pan-cancer." (PMID 38911364, 2024). "The correlation analysis revealed that the CNVs of PLBD1 was positively correlated with its mRNA expression in multiple cancers including GBM." (PMID 38911364, 2024). "Considering the abnormal expression of PLBD1 in pan-cancer, we further showed the genetic alteration status of PLBD1 across pan-cancer samples in TCGA datasets." (PMID 38911364, 2024). "To reveal the relationship between PLBD1 expression and the prognosis of patients, we conducted the prognostic analysis in pan-cancer." (PMID 38911364, 2024). "Furthermore, we exhibited a significant correlation between PLBD1 expression and the pathological stages of some cancers, including LIHC, PAAD, READ and THCA." (PMID 38911364, 2024). "In conclusion, PLBD1 may serve as a potential therapeutic target for cancer therapy, indicating immune infiltration and poor prognosis of cancer patients." (PMID 38911364, 2024). "Moreover, analysis of TCGA dataset revealed high expression of PLBD1 in multiple cancers, including LGG and GBM." (PMID 38911364, 2024). "In addition, PLBD1 expression was significantly negatively correlated with T cell recognition of cancer cells (step 6), which may be due to significantly increased expression of several inhibitory immune checkpoints in the PLBD1 high expression group." (PMID 38911364, 2024). "Therefore, PLBD1 may be a potential biomarker for predicting the response to immunotherapy in patients with malignant tumors." (PMID 38911364, 2024). "After integrating GTEX data, there were 23 cancer types with statistically significant PLBD1 expression in normal tissues and tumors." (PMID 38911364, 2024).
cardiovascular diseases (1 paper, 2024). "Previous literature suggests a link between PLBD1 and cardiovascular diseases." (PMID 38911364, 2024).
PLBD1 also shares sentences with these, for which no sentence is quoted: pancreatic ductal adenocarcinoma (3 papers); cystic fibrosis (1); infarction (1); lung carcinoma (1); mastitis (1).